CCL5 (C-C motif chemokine ligand 5)
Diseases named in the same sentence as CCL5 in open-access papers (continued):
Sharing a sentence is not in itself a finding about the gene and the disease.
tumor (continued). "Increased expression of Ccl5 promotes tumour proliferation and metastasis, high expression of Bcl2 inhibits apoptotic death, favouring neoplastic cells proliferation and Gstp1 is a marker of preneoplastic foci in liver tissue." (PMID 34650394, 2021). "High levels of CCL5 and CD68 are associated with tumour size, degree of tumour invasion, lymphatic metastasis and pathological grading." (PMID 34638423, 2021). "Knowing that CCL5 regulates the number of EVs that tumor cells secrete, we also wanted to test if it regulates the cargo of the EVs and subsequently their impact on macrophages." (PMID 34298673, 2021). "Given the reported role of CCL5 in tumor metastasis, we then directed our investigation to define the mechanisms by which MEKK1 controls CCL5 expression." (PMID 33868996, 2021). "In mice, CCL5 knockdown in MES–GBM cells reduced tumor cell survival in vitro and increased host survival in an in vivo tumor model." (PMID 33923334, 2021). "Tumour cells engaged with stromal cells via CCL5 metastasize and make a stable network at bone tissue." (PMID 34975909, 2021). "We observed only a modest partial inhibition of CCL5 reporter activity, suggesting that FGFR1-independent signaling plays a major role in tumor cell-induced CCL5 expression in mammary fibroblasts." (PMID 33868996, 2021). "Mechanistically, chemokine ligand 5 (CCL5) was identified as one of the most highly expressed chemokines by tumor cells in vivo after treatment with BJJP." (PMID 34899325, 2021). "Our results also confirmed that CCL5 and CCR5 were highly expressed in HCC tissues, and circETFA promoted tumor development by upregulating the expression of CCL5." (PMID 34716323, 2021). "PR contains vascular endothelial growth factor (VEGF) and fibroblast growth factor (FGF), which stimulate angiogenesis; TGF-beta, which promotes tumor growth; and CCL5, which is involved in cancer progression and cisplatin resistance." (PMID 33809553, 2021). "Circulatory and tumor associated levels of CCR5 and its cognate ligands (CCL3, CCL4, CCL5) were analyzed by ELISA, qRT-PCR and immunohistochemistry." (PMID 32902795, 2021). "CCR5 and its ligands, particularly CCL5 have been thought to support tumor growth either directly, by driving the migration of tumor cells to tumor sites, and mostly by recruiting MDSC and dendritic cells to the tumor site." (PMID 34944943, 2021). "M2 type macrophages closely resemble tumor-associated macrophages (TAMs) and are characterized by increased expression of IFN-γ, CCL2, CCL5, CXCL16, CXCL10, CXCL9, TNF-α, MMP9 and IL-10, arginase-1, and peroxisome proliferator-activated receptor-γ (PPAR-γ)." (PMID 33925575, 2021). "Classical monocytes recruited to tumor site by chemokines, including colony-stimulating factor 1 (CSF-1), chemokine (C-C motif) ligand 2 (CCL2), and chemokine (C-C motif) ligand 5 (CCL5), then polarized into M2 tumor-associated macrophages (TAMs)." (PMID 34141607, 2021). "In contrast, CD8+ TILs showed elevated levels of inflammatory chemokine genes, CCL3 and CCL5, which are involved in the trafficking and recruitment of other immune cell populations to hinder tumor growth." (PMID 33916009, 2021). "First, we tested if direct CCL5 stimulation of macrophages was sufficient to drive them toward a pro-tumor phenotype." (PMID 34298673, 2021). "Instead, these data suggest that CCL5 autocrine signaling promotes generation of tumor EVs that reprogram macrophages to a more metastatic, TAM function." (PMID 34298673, 2021). "Macrophages express high levels of its receptor (CCR5) and respond to CCL5 produced by tumor cells by infiltrating to the TME." (PMID 33968034, 2021). "Patient-derived tumor xenografts (PDXs) were established from two human GBMs presented with high/low CCL5 expression." (PMID 34239070, 2021). "The CCL5/CCR5 axis is involved in T cell migration and recruitment, and maintenance of M2 phenotype in tumor-associated macrophages." (PMID 36474817, 2021).
tumor (continued). "Tumor CCL5 expression was varied in tumors to determine its role in regulating macrophage biology through EVs." (PMID 34298673, 2021). "In summary, we observed that when IFN-γ was neutralised, the production of CXCL10 and CCL5 within SCC tumours was notably impaired, which correlated with a significant reduction in infiltrating CD8+ T cell numbers." (PMID 33925140, 2021). "CCL5 also enhances anti-tumor immunity and promotes immunotherapy by recruiting anti-tumor-immune cells to the tumor microenvironment." (PMID 34771505, 2021). "Several of the proteins that are regulated in TEMs and TAMs by tumor EVs and CCL5 are potential chemotactic factors for other cell types within the microenvironment such as T-regs." (PMID 34298673, 2021). "Combined with TIICs analysis, we found that the METTL14/CCL5/Tregs axis was a potential tumor immune regulative pathway in ccRCC." (PMID 34122497, 2021). "In B16-F10 mouse model of melanoma, genetic silencing of CCL5 in tumor cells completely abrogated NK cell recruitment to the tumor microenvironment (TME)." (PMID 33802954, 2021). "CXCL10, CXCL11, and CCL5 secreted by M1 TAMs, which recruit Th1, Th17, and cytotoxic T cells, exhibit anti-tumor effect." (PMID 35127700, 2021). "Tumor-infiltrating neutrophils can support adaptive immune responses by recruiting T cells to tumor sites via the secretion of chemokines, such as CCL5, CCL20, CXCL9, CXCL10 and CXCL11." (PMID 34572138, 2021). "To evaluate the clinical significance of tumor EV programming of macrophages, we looked in our data for cytokines commonly regulated by tumor EV secretion and tumor CCL5 expression." (PMID 34298673, 2021). "A promising strategy is to target the autophagy pathway by silencing Beclin1 (BECN1), leading to improved NK cell infiltration into the tumor because of increased levels of the chemokine CCL5." (PMID 34572949, 2021). "Application of 131I in a mice model which was bearing transduced MSCs with NIS under the control of RANTES/CCL5-promoter led to decreased tumor growth and increased overall survival." (PMID 34249257, 2021). "The cytokines, such as CCL5 and IL10, will also recruit regulatory T cells (Treg) to the tumor site, and appears to be negatively associated with CD8 + T cell infiltration." (PMID 34141607, 2021). "As expected, treatment with either antibody markedly decreased the expression and secretion of CCL2 and CCL5 in these tumor cells, with the most significant decrease in the combination treatment group." (PMID 33537094, 2021). "By consulting a large body of literature, we identified the CCL5 gene and found that it was closely related to the occurrence and progression of many tumours." (PMID 33247987, 2021). "Mice bone marrow-derived MSCs that secreted CC-chemokine ligand 5 (CCL5) promoted tumor cell motility, invasion and metastasis by CCL5/CCR5 signaling pathway." (PMID 33744858, 2021). "For instance, CAFs secrete growth factors such as CXCL12, HGF, EGF, IGF, IL‐6, IL‐8, IL‐11 and CCL5, which facilitate tumour growth." (PMID 33943003, 2021). "Tumour cells recognize secretary molecules i.e. CCL5 and CXCL12 released from stem cells and osteocytes." (PMID 34975909, 2021). "Expression of APM genes (β2M) and tumor immune microenvironment genes (chemokine CCL5) were also higher in patients with CB compared to NCB (unadjusted p = 0.01 and 0.02, respectively)." (PMID 34162872, 2021). "More specifically, blockade of CCL5 after tumor establishment limited the anti-tumor effect of CD40 agonism plus immune checkpoint blockade." (PMID 34030676, 2021). "In tumor tissues, T cell infiltration requires CCL5 derived from tumor cells and is amplified by CXCL9 secreted by myeloid cells induced by interferon-g." (PMID 34367971, 2021). "Accordingly, interfering pharmacologically with other macrophage chemoattractants, such as CXCL12 and CCL5, as a means of inhibiting tumor growth merits further investigation." (PMID 34603327, 2021).
tumor (continued). "A number of studies have shown differential expression of CCR5-related ligands (CCL3, CCL4, CCL5) in peripheral blood and tumor samples of CRC." (PMID 32902795, 2021). "Our data indicate, however, that antibody-treated mice did show reduced CXCL9, CXCL10, and CCL5 chemokine production within the tumour mass, and a corresponding reduction in the number of tumour-infiltrating T cells." (PMID 33925140, 2021). "In contrast, CCL5 enhances homing of Tregs in some tumor models, and the transplantable pancreatic tumor model KPC has been shown to grow less aggressively in mice lacking CCL5." (PMID 34030676, 2021). "Using the median value (50–50 division), the expression level of CXCL9, CXCL10, CXCL11, and CCL5 in tumor or adjacent normal tissues allowed the stratification of patients into groups." (PMID 34539647, 2021). "Studies by our group and others have demonstrated that CCL5 plays a critical role in the recruitment of TAMs that drive tumor metastasis as well as directly stimulating tumor progression." (PMID 34298673, 2021). "Earlier, we identified that RKIP inhibits tumor angiogenesis, F4/80+ macrophage infiltration, and lung metastasis by downregulating CCL5 expression in cancer cells." (PMID 34465801, 2021). "gaMSCs secrete several cytokines and exosomes into the tumour microenvironment, such as IL-6, CCL-5 and VEGFA." (PMID 34256854, 2021). "Blockade of CCL5 leads to decreased tumor growth in immune competent models, suggesting that T-cells are required to reduce tumor bulk." (PMID 34298673, 2021). "Indirect interactions between tumor cells and MCs caused by soluble factors produced by HRS cells, such as IL-9, IL-13, CCL5/RANTES are important for MC infiltration and proliferation." (PMID 34631562, 2021). "CCL5 transcript levels were increased in human tumours treated with AIs and protein levels of CCL5 increased 35-fold 120 h after oestrogen deprivation in cultured cells, placing CCL5 as a likely key mediator of the migration response." (PMID 34602068, 2021). "Further investigation with in vivo models showed that intratumorally administered CCL5 enhanced cytotoxic lymphocytes and the anti-tumor activity of anti-PD-L1." (PMID 34030676, 2021). "For example, CCL-5 secreted by senescent melanoma cells promotes the recruitment of tumour-infiltrating leukocytes leading to a tumour suppressive environment." (PMID 33439271, 2021). "Other approaches to restrain tumor metastasis via CCR5 inhibition include targeting CCL5 in the bone marrow via nanoparticle-delivered expression silencing, in combination with maraviroc, which augmented anti-tumor immunity." (PMID 33485378, 2021). "Collectively, the results indicated that the three CTTCs (CXCL9, CXCL11, and CCL5) were selectively regulated in tumor or adjacent normal tissues and decreased with progressive stages in CRC patients." (PMID 34539647, 2021). "Macrophages altered by tumor CCL5 expression and EVs have increased expression of several genes known to drive invasion and metastasis, including OPN, SLPI, HGF, and NRG3." (PMID 34298673, 2021). "In a recent study, it has been demonstrated that targeting Beclin1 inhibited tumor growth; in addition, for NK-cells to infiltrate the tumor bed, they relied on CCL5 overexpression by the autophagy-defective tumors." (PMID 33573362, 2021). "This leads to a cascade of transcriptional events that results in CCL5 expression in the lymphatic vasculature, allowing for the recruitment and infiltration of tumour cells." (PMID 33659922, 2021). "MDSCs are the precursor cells of bone marrow-derived DCs, macrophages and granulocytes, recruited to tumor foci by chemokines like CCL2 and CCL5 to perform tumor immunosuppressive function, together forming an immunosuppressive tumor myeloid microenvironment." (PMID 34625124, 2021). "Proteomic analysis revealed reduced tumor secretion of inflammatory factors Galectin-1, Osteopontin, CCL5, and CCL9 upon treatment with Ocoxin." (PMID 33669949, 2021).
tumor (continued). "CAFs-3 from the primary tumor showed distinct expression of other chemokines and growth factors, such as C3, CCL5, IGF1, CXCL10, CXCL9, and CXCL14, in addition to CCL19 and IGF2." (PMID 34790166, 2021). "CCL5, belonging to the C-C chemokine family, is mainly secreted by T lymphocytes, macrophages, certain types of tumor cells, and synovial fibroblasts and mainly induces the recruitment and migration of immune cells to inflammatory sites." (PMID 34484236, 2021). "CTTCs including CXCL9, CXCL10, CXCL11, and CCL5, which were differentially expressed between tumor and adjacent normal tissues, were significantly correlated with the abundance of several OTUs." (PMID 34539647, 2021). "Chemokines, like CXCL2, CXCL8 and CCL5, can mobilize and activate resting NK cells, resulting in tumor cell cytolysis." (PMID 34956878, 2021). "The protein encoded by CCL5 belongs to a group of inflammation-relevant genes, while the cytoglobin gene (CYGB) functions as a tumour suppressor gene." (PMID 34112813, 2021). "In summary, this study indicates that HIF‐1α is highly expressed in CAFs, and HIF‐1α‐expressed fibroblasts secreted CCL5 by activating NF‐κB signalling pathway, thus promoting the tumour growth of LC." (PMID 33943003, 2021). "Conversely, reduction of CCL5 expression through either CRISPR-Cas9 (BM1 cells) or CRISPR-dCas9-KRAB (LMB cells) decreased tumor EV secretion with one guide RNA." (PMID 34298673, 2021). "A previous study involving treatment of murine tumours with tamoxifen suggested tamoxifen abrogated macrophage influx by reducing CCL2/CCL5 levels and reversed macrophage activation." (PMID 34602068, 2021). "Its ligands CCL3, CCL4, and CCL5 are broadly expressed by a variety of normal cells and tumor cells, and frequently upregulated in tumor tissues of various types of cancer." (PMID 34885241, 2021). "An alternative approach to increase NK cell infiltration into tumours has been achieved via lentivirus-mediated upregulation of CCR5 in engineered NK cells in combination with a CCL5 armed vaccinia virus." (PMID 34888493, 2021). "Patient tumours showed elevated CCL5 expression compared to the normal brain, suggesting the expression is upregulated in the course of malignant transformation." (PMID 33803414, 2021). "High expression of CXCL9 accelerated the generation of CCL5 in tumor microenvironment, and tumors with elevated expression of CXCL9 and CCL5 showed higher immunoreactivity and immune checkpoint inhibition response." (PMID 33854600, 2021). "Our current findings further suggest an additional benefit of cGAS-STING-IRF3 axis activation owing to increased expression of the CXCL10 and CCL5 chemokines, leading to T cell tumor infiltration." (PMID 34488791, 2021). "Next, we found that CCL5 was an important factor in CAFs promoting tumour growth, and NF‐κB signalling pathway was involved in enhancing CCL5 secretion." (PMID 33943003, 2021). "Apart from monocyte recruitment, CCL5 has a direct effect on tumor cells, supporting tumor cells migration, invasion, and survival." (PMID 34988021, 2021). "Here, upregulation of CCL5 in lymphatic endothelial cells promotes further tumor cell dissemination." (PMID 31963450, 2020). "CRC patients with a low number of infiltrating CD8+ T cells into tumor tissues expressed high levels of both CCL5 and S100a9." (PMID 32630699, 2020). "CCL5, secreted by tumor-infiltrating CD4 T cells, also facilitates the FAS-FASLG mediated CD8 T-cell apoptosis in gastric cancer." (PMID 33381115, 2020). "CCL5 is derived from macrophages, synovial fibroblasts, T lymphocytes and certain types of tumor cells, and plays crucial roles in the recruitment of certain leukocytes such as T cells, macrophages, and polymorphic nuclear cells, to inflammatory sites." (PMID 31693828, 2020). "Antibodies against CCL2/CCR2 and CCL5 have been employed in preclinical models in combination with checkpoint blockade immunotherapy with encouraging results in several tumor types." (PMID 32580431, 2020).
tumor (continued). "Intratumoral LCMV administration in Ma-Mel-86a tumors established in NOD/SCID mice led to a significant upregulation of CCL5 at the transcriptional level, while in Ma-Mel-51 tumor bearing mice the CCL5 mRNA levels remained unchanged." (PMID 32973762, 2020). "Conditioned medium from cHL cells increases CCL5 secretion by bone marrow MSCs (tumor-educated MSCs)." (PMID 32630699, 2020). "Macrophage treatment with these nanocomplexes did not reduce their viability and efficiently stimulated the secretion of the T-cell recruiter chemokines CXCL10 and CCL5, of great importance for an effective anti-tumor immune response." (PMID 32733469, 2020). "In parallel, in a research system based on HER2 down-regulation that has led to generation of residual tumors and then to tumor recurrence, CCL5 induced elevated presence of macrophages that promoted emergence from dormancy." (PMID 33585241, 2020). "By modulating CCL5 expression, miR-147 inhibits tumor cell growth, migration, and invasion in vitro." (PMID 32630699, 2020). "These patients have strong CCL5 immunohistochemistry staining in tumor tissues and in metastatic lymph nodes." (PMID 32630699, 2020). "In accordance with our previous findings, treatment with anti-CCL5 antibody reduced the infiltration of Treg cells in tumor tissues, but the addition of PD-L1 antibody did not augment the effect." (PMID 32300119, 2020). "In this study, it was found that tumor-derived CCL5 has recruited effector T cells to tumors; the release of IFNγ by T cells has increased the production of CXCL9 by macrophages, leading to increased immune surveillance of the tumors." (PMID 32582148, 2020). "Gene-gene interactions were detected in the relapse group; CCL5, GZMB, IL2RA, SELE, and CCL8 interacted with CCR5 in both the pCR and relapse groups and were associated with tumour progression, and metastasis." (PMID 33138797, 2020). "Endothelial cells, by secreting CCL5, also inhibit androgen receptor signaling and promote tumor cell invasion." (PMID 32630699, 2020). "Depletion of CD8+ T cells completely counteracted the effects of tumor inhibition produced by the combination of anti-PD-L1 and anti-CCL5 antibodies, indicating that CD8+ T cells are critical for the antitumor effects of the combination treatment." (PMID 32300119, 2020). "It is also been reported that CCL5 released by tumor cells acts its function via paracrine signaling to attract NKs to the tumor bed." (PMID 32508531, 2020). "By secreting CCL5, tumor cells recruit CCR5+ monocytes/macrophages, which induce angiogenesis through VEGF secretion." (PMID 32630699, 2020). "Snail expressed tumor cells not only recruited macrophages by secreting cytokines such as CCL2, CCL5, and IL-6, but also secretes tumor-derived exosomes (TEXs) which contains miR-21 to induce M2-type polarization of macrophages." (PMID 33224886, 2020). "CCL5 is responsible for the infiltration of a tumor by NK cells, conventional type 1 dendritic cells, T helper cell type 1 (Th1), and type 1 cytotoxic cells (Tc1)." (PMID 33076281, 2020). "CCL5 belongs to the CC family of chemokine and is mainly expressed in T cells, macrophages and some tumor cells." (PMID 33173412, 2020). "It was also reported that CCL5 promoted VEGF-dependent tumor angiogenesis in the human osteosarcoma microenvironment by activating the hypoxia-inducible factor (HIF)-1α signaling cascades." (PMID 32443699, 2020). "Several studies have focused on the effect of CCL5 on tumors, finding that CCL5 can significantly promote tumor growth, metastasis, angiogenesis, and immune escape." (PMID 32081834, 2020). "IFNα was also induced along with the inflammatory chemokines CXCL10, and CCL5, and their expression mirrored the kinetics of viral replication in the tumor in vivo and in vitro." (PMID 32581235, 2020).